ESM1 (endothelial cell specific molecule 1)
Diseases named in the same sentence as ESM1 in open-access papers (continued):
Sharing a sentence is not in itself a finding about the gene and the disease.
gastric cancer (17 papers, 2016 to 2025). A primary or metastatic malignant neoplasm involving the stomach. "Several studies have previously reported the overexpression of ESM1 in gastric cancer and its potential role as a prognostic marker, associated with tumor stage, lymph node metastasis, and poor clinical outcomes." (PMID 40506951, 2025). "Recent studies have shown that ESM1 overexpression in gastric cancer cells can trigger EMT through activation of the TGF-β and β-catenin signaling pathways." (PMID 40506951, 2025). "In conclusion, ESM1 is expected to be a therapeutic target for the peritoneal metastasis of gastric cancer." (PMID 38201620, 2023). "The expression of ESM1 is up-regulated in gastric cancer tissues, and even higher in primary gastric cancer with peritoneal metastasis." (PMID 38201620, 2023). "The conditioned medium of gastric cancer cells overexpressing ESM1 promoted tube formation in vitro and gastric cancer cells overexpressing ESM1 induced angiogenesis in vitro." (PMID 38201620, 2023). "ESM1 was highly expressed in gastric cancer tissues and was significantly correlated with prognosis and MVD." (PMID 38201620, 2023). "We further demonstrated that ESM1 acted as a secreted protein that significantly promoted the angiogenesis and metastasis of gastric cancer both in in vivo and in vitro by co-culture assays." (PMID 38201620, 2023). "To further examine the expression level of ESM1 in gastric cancer tissues, we detected 77 paired adjacent and GC tissues by RT-qPCR, and the results showed that ESM1 expression was higher in gastric cancer tissues than in adjacent tissues." (PMID 38201620, 2023). "GEO datasets (GSE26942 and GSE66229) and the TCGA database further confirmed that ESM1 was highly expressed in gastric cancer tissues." (PMID 38201620, 2023). "This study found that ESM1 was highly expressed in gastric cancer tissues and positively correlated with microvessel density (MVD)." (PMID 38201620, 2023). "Herein, we demonstrated that ESM1 expression was significantly upregulated in gastric cancer tissues and positively correlated with platelet endothelial cell adhesion molecule-1 (CD31) levels." (PMID 38201620, 2023). "To investigate the effect of ESM1 secreted by gastric cancer cells on endothelial cells, we treated endothelial cells with gastric cancer cell culture supernatant to detect the effect on their functional behaviors." (PMID 38201620, 2023). "In gastric cancer, ESM-1 is strikingly overexpressed in tumor tissue, resulting in tumor proliferation, distant lymph nodes metastasis, as well as vascular invasion." (PMID 34109132, 2021). "In gastric cancer, researchers found that tumors with ESM-1 overexpression show more easily invasion into vascular, causing more frequently distant metastasis." (PMID 34109132, 2021). "In gastric cancer, ESM-1 mRNA was significantly up-regulated in cancer tissues than that in adjacent normal tissues, and high ESM-1 level was associated with distant metastasis, Borrmann type IV and vascular invasion." (PMID 28514746, 2017). "In this study, we found that ESM1 was significantly upregulated in cervical cancer, ESM1 was reported to regulate tumor progression in many cancer types including non-small-cell lung cancer, ovarian cancer, gastric cancer, and hepatocellular carcinoma." (PMID 38954708, 2024). "We next investigated the role of ESM1 in gastric cancer metastasis." (PMID 38201620, 2023). "Mechanistically, ESM1 is secreted by gastric cancer cells to act with the membrane receptor c-Met on endothelial cells, which subsequently activates the MAPK signaling pathway and promotes the expression of pro-angiogenic factors, thereby promoting angiogenesis and peritoneal metastasis." (PMID 38201620, 2023). "Moreover, clinical validation, in in vitro and in vivo experiments, confirmed that ESM1 promoted gastric cancer angiogenesis, eventually promoting gastric cancer peritoneal metastasis." (PMID 38201620, 2023).
gastric cancer (continued). "In conclusion, ESM1 expression is increased during the peritoneal metastasis of gastric cancer." (PMID 38201620, 2023). "Endothelial-specific molecule 1 (ESM1) was found to be significantly associated with gastric cancer peritoneal metastasis (GCPM); however, the biological functions and molecular mechanisms of ESM1 in regulating GCPM remain unclear." (PMID 38201620, 2023). "The present study found that ESM1 could regulate angiogenesis and promote peritoneal metastasis in gastric cancer." (PMID 38201620, 2023). "Moreover, in a study of 159 gastric carcinomas, ESM-1 protein was detected in the tumor epithelium in more than half of samples, particularly in the tumor cell plasma membrane." (PMID 26809958, 2016). "In addition, ESM1 greatly improved the sensitivity and specificity of the gastric cancer diagnosis." (PMID 38201620, 2023). "Additionally, serum ESM-1 was more sensitive than CEA for the diagnosis of gastric cancer." (PMID 28514746, 2017). "In conclusion, our findings identified the role of ESM1 in gastric cancer angiogenesis and GCPM, thus providing insights into the diagnosis and treatment of advanced gastric cancer." (PMID 38201620, 2023). "Differential expression analysis showed that IGFBP7, CCN2, ESM1, CCN4 and CCN6 mRNA were over-expressed in gastric cancer tissues while CCN5 mRNA was down-expressed (all p < 0.05)." (PMID 37304887, 2023). "In gastric cancer, ESM-1 overexpressed endothelial cells HMEC-1 and adenocarcinoma cells MKN28 are treated with a goat polyclonal antibody (PABsc-20343) to antagonize ESM-1." (PMID 34109132, 2021). "In the bulk gastric cancer tissue microarray data, CD34 shows a high correlation with other vascular markers, ESM 1 and PECAM1." (PMID 32293340, 2020). "Endothelial cell-specific molecule 1 (ESM1), a proteoglycan secreted by endothelial cells after activation, has been shown to be widely involved in the growth and metastasis of many tumors, including gastric cancer, kidney cancer, and liver cancer." (PMID 36117773, 2022). "Also, ESM1 has been found to promote angiogenesis in CRC and HCC but not in gastric cancer." (PMID 38201620, 2023).
hepatocellular carcinoma (17 papers, 2013 to 2026). A malignant tumor that arises from hepatocytes. "The inhibition of ESM1 can reduce angiogenesis and metastasis and attenuate the drug resistance of hepatocellular carcinoma (HCC)." (PMID 38201620, 2023). "ESM1 expression in cancer is correlated with bad prognosis in human gastrointestinal and hepatocellular carcinomas." (PMID 36248978, 2022). "ESM1 has been widely explored in various cancers, including prostate cancer, hepatocellular carcinoma, and head and neck squamous cell carcinoma; it also has prognostic value in esophageal cancer." (PMID 35769999, 2022). "ESM-1 expression significantly affects the migration of cells in colorectal, gastric, nasopharyngeal, head and neck cancer, and hepatocellular carcinomas." (PMID 34109132, 2021). "It had been reported that knockdown of ESM1 gene expression by transfecting SK-Hep1 hepatocellular carcinoma cells with ESM1 siRNA showed 1.6-fold and 2.2-fold decreased abilities of migration and invasion." (PMID 28108731, 2017). "ESM1, also known as endocan, has been shown to regulate endothelial cell function in the initiation and progression of human cancers, including esophageal cancer, hepatocellular carcinoma, bladder cancer, and breast cancer." (PMID 34745101, 2021). "Moreover, immunohistochemical studies have shown that elevated ESM-1 expression correlates with unfavorable prognoses in different types of cancers, including glioblastoma, colon cancer, and hepatocellular carcinoma, as well as RCC." (PMID 29416643, 2018). "In hepatocellular carcinoma (HCC), researchers have reported that histone lactylation activates the transcription of ESM1 in HCC cells and that ESM1 is highly expressed in HCC, where it plays a carcinogenic role." (PMID 39620228, 2024). "For example, RGCC, SPP1 (osteopontin), GPNMB, and APOE are highly expressed in hepatocellular carcinoma (HCC), whereas PLVAP (PV1), CD276 (B7-H3), and ESM1 are predominantly expressed in glioblastoma (GBM)." (PMID 41303611, 2025). "Moreover, over-expression of ESM1 had been reported to be correlated with vascular endothelial growth factor, which could therefore represented as a biomarker of endothelial cell activation in response to pro-angiogenic signals from hepatocellular carcinoma." (PMID 28108731, 2017). "Indeed, from TCGA data we found that ESM1 was upregulated in many cancer types compared to normal tissue including hepatocellular carcinoma, we also confirmed the increased ESM1 expression in HCC sample with our HCC samples." (PMID 38956432, 2024). "Recent studies have revealed that ESM1 may participate in the occurrence and development of such cancers as head and neck squamous cell carcinoma (HNSCC), hepatocellular carcinoma (HCC) and bladder cancer (BLCA) in human." (PMID 37100467, 2023). "Here in hepatocellular carcinoma, we used in vivo experiments to demonstrate that cancer cells express Esm1 to inhibit CD4+T cells mediated cancer cytotoxicity, which supports the anti-inflammatory role of ESM1 in HCC development." (PMID 38956432, 2024).
prostate carcinoma (15 papers, 2017 to 2024). A carcinoma that arises from epithelial cells of the prostate gland. "Elevated ESM1 readings have been shown to be associated with prostate cancer progression and metastasis, ESM1 over-expression correlates to a higher Gleason Score." (PMID 36831619, 2023). "So, we conducted this study to investigate the prostate cancer cells in vitro and in vivo to explore the function and underlying molecular mechanisms of ESM1 on human prostate cancer cells." (PMID 28108731, 2017). "It had been reported that ESM1 was associated with several types of malignancies, but the roles of ESM1 on prostate cancer remained unclear." (PMID 28108731, 2017). "In addition, ESM-1 is involved or implicated in prostate cancer, endothelial injury in respiratory distress syndrome, oral cancer, erectile dysfunction, and pulmonary infection." (PMID 30237882, 2018). "In prostate cancer, ESM1 maintains tumor cell stemness and metastasis by activating the Wnt/β-Catenin signaling pathway." (PMID 37476182, 2023). "Endothelial cell-specific molecule 1 (ESM1), normally a secreted proteoglycan, stimulated the formation of prostate cancer CSCs through β-catenin when localized in the nucleus." (PMID 34685470, 2021). "Of note, multiple genes hitherto known to be associated with prostate cancer progression were observed in the top list of upregulated entities including but not limited to MYBL2, ESM1, PBK, and UBE2C in PC3, and MMP1, CCL5, and STC1 in DU145." (PMID 31493351, 2019). "Additional studies are required to determine the mechanisms underlying the decreased expression of CXCL3 in endocan siRNA silenced PC-3 cells, and more research is needed to ascertain the biological role of ESM-1 in prostate cancer." (PMID 28533735, 2017). "Western blot analysis and qRT-PCR detected ESM1 protein in four of the prostate cancer cell lines (PC3, DU145, 22Rv1 and LNCap) examined." (PMID 28108731, 2017). "We further confirmed that ESM1 knockdown on the growth and metastasis of prostate cancer cells in vitro and in vivo, suggesting the tumor suppressor role of ESM1 in prostate cancer." (PMID 28108731, 2017). "In our study, knockdown of ESM1 showed up-regulation of cyclin D1 and down-regulation of p21 with the results of increased proliferation of prostate cancer cells." (PMID 28108731, 2017). "Additional studies are required to ascertain the biological role of ESM-1 in prostate cancer cells and the link with the expression of CXCL3." (PMID 28533735, 2017). "This may be attribute to the imbalance of MMP-9/TIMP-1, which is the mechanism of ESM-1 promoting metastasis of prostate cancer cells." (PMID 34109132, 2021). "Therefore, we considered that there seem to be another mechanism modulated by ESM1 against the progression of prostate cancer." (PMID 28108731, 2017). "We found that ESM1 knockdown in prostate cancer cells resulted in increased cell proliferation and colony formation ability response evidenced by decreased expression of p21 and increased expression of cyclin D1 in prostate cancer cells." (PMID 28108731, 2017). "Being different from these previous studies, our study indicated that inhibiting the expression of ESM1 could enhance cell growth by modulating cell-cycle related proteins of prostate cancer cells." (PMID 28108731, 2017). "Additionally, ESM1 knockdown increased in vivo tumorigenicity and metastasis of prostate cancer cells." (PMID 28108731, 2017). "Taken together, ESM1 could play a tumor suppressing role against the growth, proliferation, and metastasis of prostate cancer cells in this study, which was contrary to previous studies." (PMID 28108731, 2017). "In conclusion, although the precise mechanism by which ESM1 exerted its effects on the progression of prostate cancer remained to be determined, our present findings suggested that ESM1 could modulate the progression of prostate cancer by methods as tumor suppression in this study." (PMID 28108731, 2017).
prostate carcinoma (continued). "Because inhibition of ESM1 could enhance the abilities of proliferation, migration and invasion of prostate cancer cells in vitro, it was necessary to examine whether this effect could enhance the progression of prostate cancer cells in vivo." (PMID 28108731, 2017). "Another study revealed that the knockdown of endothelial cell specific molecule-1 promoted tumorigenicity and metastasis through the regulation of MMP2/MMP9 in prostate cancer cells." (PMID 31777601, 2019). "The human prostate cancer cell line PC3 and DU-145 were further validating the effect of ESM1 on the migratory and invasive behavior of prostate cancer cells." (PMID 28108731, 2017). "Thus, in the meta-analyses of prostate cancer, we explored two top gene sets whose GSAS were driven by ESM1, and by SMC6, CDT1 and RAD18." (PMID 38597610, 2024). "In prostate cancer, ESM-1 expression is significantly elevated in patients with high Gleason grades and Gleason scores, the main method used to stage prostate cancer, suggesting ESM-1 is a useful biomarker for cancer diagnosis." (PMID 34109132, 2021). "However, there are no studies regarding the mechanism of ESM1 in prostate cancer." (PMID 28108731, 2017).
Sepsis (13 papers, 2015 to 2024). Sepsis is defined as life-threatening organ dysfunction caused by a dysregulated host response to infection. "Endothelial cell-specific molecule 1 (ESM-1), a soluble dermatan sulfate proteoglycan, also known as endocan, serves as a diagnostic and prognostic indicator due to its aberrant expression under pathological conditions, including cancer, sepsis, kidney diseases, and cardiovascular disease." (PMID 34109132, 2021). "ESM-1 is a soluble proteoglycan secreted by endothelial cells, which is regulated by vascular endothelial growth factor and pro-inflammatory cytokines in sepsis patients and COVID-19 patients." (PMID 39201697, 2024). "A great number of studies have reported that ESM-1 is a novel biomarker for sepsis severity stratification and mortality." (PMID 37373282, 2023). "ESM-1 is a very important biomarker in sepsis and a novel biomarker in COVID-19; however, in our study it seems that its prognostic value was restricted by older age and the severity of the symptom manifestations." (PMID 37373282, 2023). "Plasma ESM1 levels correlate with inflammation severity and poor survival in coronary artery disease, chronic kidney disease, IgA nephropathy, and sepsis." (PMID 32781625, 2020). "Accumulating evidence suggests that ESM1 has prognostic value in pathological conditions including cancer, sepsis, inflammatory disorders, hypertension, transplant rejection, and chronic kidney disease." (PMID 32781625, 2020). "ESM-1 is overexpressed in obesity, during sepsis, and under inflammatory conditions, as well as in malignant tumors, and ESM-1 is associated with cardiovascular disease." (PMID 29416643, 2018). "Here, we focused on soluble plasma proteins that have been described to increase during the course of sepsis (sCD163 and sTREM-1) and as result of inflammatory conditions (endocan/ESM-1)." (PMID 26263001, 2015). "This is congruent with the observation that ESM-1 levels are strongly upregulated only at later stages of severe sepsis and organ dysfunction." (PMID 26263001, 2015). "ESM-1 does remain an important prognostic biomarker in sepsis." (PMID 37373282, 2023). "However, the concentration of ESM-1 is reportedly increased during chronic diseases such as Coronary Artery disease, chronic inflammatory conditions such as Systemic Lupus Erythematous and acute severe infections such as sepsis." (PMID 37161496, 2023). "Thus, ESM-1 could be regarded as a biomarker for hypertension, sepsis, malignancy, and PE." (PMID 36675388, 2023). "Together with currently discussed cell-activation markers (sTREM-1, ESM-1, cfDNA, monocyte responsiveness) we wanted to establish differences in the immune status of the cardiac surgery patients that have an uneventful recovery and those that develop SIRS/sepsis for timely intervention." (PMID 26263001, 2015). "ESM-1 levels were measured in all patients recruited in the study, within the first 24 h of ICU admission (critically ill COVID-19 patients and critically ill non-septic patients), or 6 h following sepsis diagnosis (critically ill septic patients)." (PMID 37373282, 2023).
glioblastoma (12 papers, 2012 to 2025). The most malignant astrocytic tumor (WHO grade IV). "As a biomarker of neovascularization, ESM1 overexpression is also often used as an indicator of tumor progression and metastasis in certain malignances, such as glioblastoma, renal cell carcinoma, and non-small cell lung cancer." (PMID 27683113, 2016). "In MG3, genes involved in endothelial regulation (ESM1, APLN, ALCAM) and ligands for αVβ3 integrin (EDIL3 and POSTN) were expressed at higher levels compared to MG1 and MG5, the latter of which recruit tumour-associated macrophages (TAM) in adult glioblastoma." (PMID 37679810, 2023). "It is important to note that global loss of Esm1 does not cause a noticeable defect in the brain or other organs, so systematically diminishing or even eliminating tumor-associated Endocan could indeed be a promising strategy to control glioblastoma progression and recurrence." (PMID 39773984, 2025). "Because ISH staining for the prototypical endothelial marker CD31 (PECAM1) is not available in the Ivy GAP, analysis of glioblastoma vasculature considered ESM1, MECOM, and ENPEP; genes known to be enriched in endothelial cells." (PMID 39724753, 2024).